LOX (lysyl oxidase)
Diseases named in the same sentence as LOX in open-access papers (continued):
Sharing a sentence is not in itself a finding about the gene and the disease.
ovarian carcinoma (continued). "LOX is positively expressed in 97.6% (40/41) epithelial ovarian cancer, 80% (16/20) borderline ovarian cancer, 48.1% (13/27) benign ovarian cancer and 7.1% (2/28) normal ovarian tissues." (PMID 23545606, 2013). "Simultaneously, in vitro tests revealed that LOX might play a role in the initiation and progression of ovarian cancer by regulating cell proliferation, migration, and gene expression." (PMID 38339384, 2024). "Serum LOX levels were significantly higher in ovarian cancer patients as compared to control and could serve as biomarker for the diagnosis of ovarian cancer patients." (PMID 35054220, 2021). "Serum LOX level was significantly higher in ovarian cancer patients as compared to control." (PMID 35054220, 2021). "Under hypoxic stress, HIF-1 could promote the expression of COL1A1 in the mesothelial cells and the expression of LOX in both the mesothelial and cancer cells, which remodels collagen to accelerate the invasion of ovarian cancer." (PMID 35004308, 2021). "The detailed mechanisms of LOX mediated tumerigenesis in ovarian cancer are yet to be understood." (PMID 35054220, 2021). "This study was conducted with the objective to evaluate the pattern of LOX gene polymorphism and serum LOX enzyme levels in patients with ovarian cancer and to compare them with non-cancer control subjects." (PMID 35054220, 2021). "Low oxygen tension stimulates the activation of the hypoxia‐inducible factor(HIF)pathway in the metastatic microenvironment of ovarian carcinoma and subsequently elevates LOX expression in a HIF‐dependent pattern to facilitate collagen remodeling and tumor invasion." (PMID 33058284, 2020). "Furthermore, the dual prostaglandin-endoperoxide synthase/lipoxygenase (COX/LOX) inhibitor licofelone improved the efficacy of paclitaxel in ovarian cancer by suppressing tumor stem-like properties." (PMID 31193124, 2019). "We hypothesized that hypoxia-induced LOX upregulates the expression of HIF-1α which promotes ovarian cancer cell invasion and metastasis." (PMID 23545606, 2013). "Since hypoxia followed by reoxygenation may also provide a physiological pressure in tumors selecting for metastatic cell phenotypes, it is essential to determine whether hypoxia-induced LOX in ovarian cancer cells is active under hypoxic conditions." (PMID 23545606, 2013). "Additionally, LOX is expressed intracellularily within ovarian cancer cells and facilitates cell migration through the regulation of HIF-1α." (PMID 23545606, 2013). "Serum LOX levels could be a potential biomarker for the diagnosis and prognosis of ovarian cancer." (PMID 35054220, 2021). "To determine whether LOX and HIF-1α expression increases in ovarian cancer tissues, we examined the expression of LOX and HIF-1α in 44 cases of human epithelial ovarian carcinoma, 20 cases of borderline ovarian tumor, 27 cases of benign ovarian tumor and 28 cases of normal ovarian tissues." (PMID 23545606, 2013). "Lysyl oxidase (LOX) has been proven to act as a tumour promoter and regulate by HIF-1α in ovarian cancer." (PMID 35004308, 2021). "Our study intended to evaluate the prognostic value of lysyl oxidase (LOX) and its four relevant members, the lysyl oxidase–like genes (LOXL1‐4), in ovarian cancer (OC) patients." (PMID 33058284, 2020). "Previously, we described increased expression of LOX in PAC and TOP resistant ovarian cancer cell lines, and its expression was upregulated in ALDH1A1 positive cells." (PMID 32283808, 2020). "The terms “Epithelial-mesenchymal transition” and “Integrin cell surface interactions” are significantly enriched in mesothelioma but not in ovarian cancer, suggesting that the changes in LOX and LOXL interactome associated with cancer might depend on the cancer type." (PMID 33383846, 2020). "Specifically, hypoxic signaling increased expression of lysyl oxidase (LOX) in mesothelial and ovarian cancer cells to promote collagen crosslinking and tumor cell invasion." (PMID 32963283, 2020).
ovarian carcinoma (continued). "In this report we have studied the expression of LOX, collagens, and ALDH1A1 in drug-resistant ovarian cancer cell lines." (PMID 30583585, 2018). "In this study, we described expression of another ECM molecule—LOX—in PAC- and TOP-resistant ovarian cancer cell lines." (PMID 30583585, 2018). "In the present study, we found that ROS accumulation in ovarian carcinoma cells upregulated HIF-1α expression and subsequent transcriptional induction of lysyl oxidase (LOX) which repressed E-cadherin." (PMID 25174950, 2014). "HIF-1α and LOX were knocked down in epithelial ovarian cancer cells (EOC), and HIF-1α/LOX regulation mechanism and LOX catalytic activity under hypoxia/reoxygenation microenvironment were explored." (PMID 23545606, 2013). "To study how hypoxia affects LOX and HIF-1α expression, we exposed the ovarian cancer cell lines HO8910-PM, HO8910, COC1 and SKOV3 in 1% oxygen to mimic hypoxia condition." (PMID 23545606, 2013). "In conclusion, our study demonstrates that hypoxia-HIF-1α-LOX-AKT pathway regulates the invasion and migration of ovarian cancer cells under hypoxic/reoxygenation microenvironments." (PMID 23545606, 2013). "The ovarian cancer patients had a higher level of LOX as compared to the non-cancer healthy control group, which was found to be statistically significant (p = 0.0001)." (PMID 35054220, 2021). "Our study intended to evaluate the prognostic value of lysyl oxidase (LOX) and its four relevant members, the lysyl oxidase‐like genes (LOXL1‐4), in ovarian cancer (OC) patients with various clinicopathological characteristics, which was based on the Kaplan‐Meier plotter database." (PMID 33058284, 2020). "The expression of LOX, collagens, and ALDH1A1 was also detected in ovarian cancer lesions." (PMID 30583585, 2018). "The data indicate that LOX and HIF-1α expression is related to ovarian cancer malignancy." (PMID 23545606, 2013). "The results demonstrated that migration and invading capability in ovarian cancer cells increase under hypoxia condition as compared with those under normoxia condition without LOX siRNA transfection." (PMID 23545606, 2013). "Collectively, our study demonstrates that the hypoxia-HIF-1α, LOX-FAK/AKT pathway regulates the migration and invasion of epithelial ovarian cancer cells under hypoxia/reoxygenation conditions, thus, promoting metastasis of ovarian cancer." (PMID 23545606, 2013). "Hence, LOX and LOXL-2 inhibition is a promising therapeutic target for ovarian cancer." (PMID 35054220, 2021). "There is no report on the role of LOX in migration and invasion in ovarian carcinoma." (PMID 23545606, 2013). "However, there is no research on the role of LOX in hypoxia of ovarian cancer." (PMID 23545606, 2013).
lung carcinoma (27 papers, 2012 to 2026). "In lung cancer, the high expression of LOX associated with tumor infiltration is a prognostic marker for patients with early lung adenocarcinoma." (PMID 36293126, 2022). "The results showed that a high expression of LOX was closely related to the poor prognosis of lung cancer patients, and was more associated with lung adenocarcinoma patients but not lung squamous cell carcinoma patients." (PMID 29472856, 2018). "Association of c-Raf with LOX-PP in the H1299 lung cancer line was monitored using GST-pull down assays." (PMID 22438909, 2012). "For example, LKB1 is involved in the HIF/LOX pathway through collagen type IV and β1 integrins resulting in enhanced lung cancer cell proliferation and invasiveness." (PMID 37745301, 2023). "Their study also revealed that miR‐200 and ZEB1 can affect the migration ability of mesenchymal lung cancer cells in vitro through direct regulation of LOX proteins." (PMID 36684109, 2023). "LOX was found to be overexpressed in lung cancer and in many other cancer types, and it is correlated with tumor metastasis." (PMID 34200480, 2021). "In contrast, the roles of LOX- or LOX-derived lipid mediators in lung cancer, especially KRAS-driven lung cancer, remain to be elucidated." (PMID 34635780, 2021). "For example, LOX (lysyl oxidase) has been shown to be overexpressed in lung cancer, and inhibition of LOX activity decreases the number of lung metastases." (PMID 33273919, 2020). "Metastatic lung cancer has been shown to have increased linearity of collagen fibers and organization that correlated with increased expression of the lysyl oxidases, LOX and LOXL2." (PMID 31121900, 2019). "In experimental models of lung cancer, LOX promotes tumor progression and is targeted by the tumor suppressor gene LKB1." (PMID 23409704, 2013). "The anti-cancer peptide LOX-PP, which was found to interact with c-Raf in lung cancer cells, repressed the induction of AP-1." (PMID 22438909, 2012). "The ability of LOX-PP to inhibit this pathway and the observation that lung cancers are typified by greatly reduced levels of LOX gene expression, suggests the potential use of LOX-PP in therapy of these cancers." (PMID 22438909, 2012). "LOX-PP reduced expression of Blimp1 by binding to c-Raf and inhibiting activation of AP-1, thereby attenuating the migratory phenotype of lung cancer cells." (PMID 22438909, 2012). "In addition, LOX-PP can inhibit the transformation of H1299 lung cancer cells by decreasing B-cell lymphoma-2 (BCL-2) transcription." (PMID 36293126, 2022). "Targeting LOX by inhibition was shown to decrease lung cancer progression." (PMID 34200480, 2021). "In hypoxia, HIF-1α promotes cell migration and invasion by inducing multiple genes, including the stromal cell-derived factor-1/C-X-C motif chemokine receptor-4 (SDF-1/CXCR-4) axis, C-C motif chemokine receptor 7 (CCR7), and lysyl oxidase (LOX) in lung cancer cells." (PMID 31061665, 2019). "Thus, Blimp1 is a mediator of Ras/Raf/AP-1 signaling that promotes cell migration, and is repressed by LOX-PP in lung cancer." (PMID 22438909, 2012). "In lung cancer cells, Blimp 1 expression was induced by a Ras/c-Raf/AP-1 pathway, which could be inhibited by LOX-PP via interaction with c-Raf." (PMID 22438909, 2012). "Next, in order to assess the role of Blimp1 in LOX-PP-mediated decrease in lung cancer cell migration, we asked whether ectopic Blimp1 expression can override the observed inhibition." (PMID 22438909, 2012). "The propeptide domain of lysyl oxidase (LOX-PP) was identified as a tumor suppressor, with ability to reduce Ras signaling in lung cancer cells." (PMID 22438909, 2012). "In H1299 lung cancer cells, which contain a mutant NRAS gene, LOX-PP reduced the activation of ERK and Akt, and ability for anchorage-independent growth and invasive colony formation in Matrigel." (PMID 22438909, 2012).
lung carcinoma (continued). "As the amino terminal LOX-PP domain of Pro-LOX has the ability to inhibit Ras-mediated transformation of NIH 3T3 cells and H1299 lung cancer cells, its ability to reduce Blimp1 was next examined." (PMID 22438909, 2012). "Thus, ectopic pre-LOX and LOX-PP expression in H1299 lung cancer and PANC-1 pancreatic cancer cells inhibited growth in soft agar and migration and reduced activation of ERK and Akt, with LOX-PP showing substantially higher activity." (PMID 23750284, 2013). "In this context, in a recent study focused on lung cancer, chemotherapy-induced remodeling of the ECM occurred with the pivotal intervention of host T cells which, stimulated by paclitaxel, increased their release of lysyl oxidase, favoring the formation of tumor metastases." (PMID 35205760, 2022).
aortic aneurysm (26 papers, 2013 to 2025). A ruptured aneurysm located in the wall of the proximal portion of the descending aorta proceeding from the arch of the aorta. "Studies have shown that LOX has an important function in the cardiovascular system and that LOX inactivation can cause aortic aneurysms in mice." (PMID 35498004, 2022). "LOX plays an important role in the development and function of the cardiovascular system, and LOX inactivation is associated with the formation of aortic aneurysm and AD." (PMID 36291545, 2022). "Expression of LOX is also associated with increased aortic stiffness, whereas low LOX plasma concentrations or low extracellular activity of LOX are linked to aortic rupture and aortic aneurysm, specifically in the context of an activated renin–angiotensin–aldosterone system (RAAS)." (PMID 35885053, 2022). "Low or null LOX enzymatic activity such as that observed in patients with LOX mutations or in LOX knockout mice is linked to cardiovascular abnormalities, mainly structural alterations in the arterial wall causing aortic aneurysms." (PMID 35328709, 2022). "Furthermore, the inhibition of collagen deposition by inhibiting lysyl oxidase exacerbated MFS aortic aneurysm and caused aortic dissection." (PMID 34769168, 2021). "Multiple LOX mutations have been shown to be associated with the occurrence of aortic dissection (AD) in humans, and LOX-knockout mice died during the perinatal period due to aortic aneurysm and rupture." (PMID 34307505, 2021). "Notably, loss of function mutations in LOX predispose to aortic aneurysms and age is the most important risk factor for aortic aneurysms, supporting the concept that loss of LOX upon ageing may have direct effects on ECM integrity and tissue stiffness." (PMID 34095157, 2021). "Global LOX deletion is embryonically lethal, resulting in structural alterations to the arterial walls and subsequent aortic aneurysms, previously making in vivo studies challenging." (PMID 39766266, 2024). "Knock-out animal models have shown a relationship between changes in LOX gene and human aortic aneurysms and dissection." (PMID 38664609, 2024). "This is in contrast with Lox-/- mice, which lack lysyl oxidase, and which also die perinatally, but show large aortic aneurysms." (PMID 33514025, 2021). "LOX gene homozygous KO mice died during pregnancy or postnatal stage, and autopsy showed large aortic aneurysms." (PMID 33807332, 2021). "The potential involvement of LOX/LOXs in aortic aneurysm was already suggested in the 1990s, when different experimental approaches in animal models supported the importance of LOX in the maintenance of the mechanical stability of the aorta." (PMID 31615160, 2019). "Animal studies in which lysyl oxidase was inhibited resulted in lathyrism, characterized by poor bone strength, weak ligaments, and increased occurrence of aortic aneurysms." (PMID 29470511, 2018). "Genetic inactivation of lysyl oxidase (Lox), an extracellular copper enzyme initiating collagen and elastin crosslinking, resulted in aortic aneurysm development through fragmented elastic fibers and high rupture rates." (PMID 23737735, 2013). "Inactivation of Lox (lysyl oxidase) has been shown to result in aortic aneurysms." (PMID 37079380, 2023). "The model was established by administering angiotensin II (Ang II) and β-aminopropionitrile (BAPN), a lysyl oxidase inhibitor, to mice to induce hypertension and degeneration of the elastic lamina, which would eventually result in the onset of an aortic aneurysm." (PMID 33007902, 2020). "Consequently, LOX is essential for cardiovascular development and function, indeed null mice have defective arterial wall structure with fragmented elastic fibres and die perinatally from aortic aneurysms." (PMID 30016650, 2019). "The abnormal expression of LOX enzymes is related to changes in ECM composition characteristic of atherosclerosis and aortic aneurysms." (PMID 34393991, 2021).
aortic aneurysm (continued). "Similarly, the pro-inflammatory Interferon gamma (IFN-γ), active in aortic aneurysm, and arteriosclerotic plaque rupture, were demonstrated to reduce LOX mRNA and activity in rat aortic smooth muscle cells, partly via transcriptional downregulation, and also by reducing the LOX mRNA half-life." (PMID 32708046, 2020). "Aortic aneurysm rupture model of mice was established by administering β-aminopropionitrile (BAPN), a lysyl oxidase inhibitor, and angiotensin II (Ang II) to induce hypertension and degeneration of the elastic lamina, which would eventually result in the onset of aneurysm rupture." (PMID 35358189, 2022). "Although experimental data support that LOX inhibition underlies AAA, in humans there is no solid evidence showing a direct causal relationship between LOX/LOXLs and aortic aneurysms, probably because human tissue specimens often come from late stages of aneurysmal disease." (PMID 31615160, 2019). "Similarly, in mice, genetic inactivation of LOX, but not that of LOXLs, leads to aortic aneurysms and spontaneous dissections, supporting that the inhibition of this specific isoenzyme could underlie the development of this disease." (PMID 31615160, 2019).